CPA1 (carboxypeptidase A1)
Diseases named in the same sentence as CPA1 in open-access papers:
CPA1 is named in the same sentence as 53 diseases in open-access papers, as found by Europe PMC text mining. Sharing a sentence is not in itself a finding about the gene and the disease. The quoted sentences say what the papers report.
pancreatitis (22 papers, 2018 to 2025). Inflammation of the pancreas. "A similar challenge arose with the CPA1 gene, for which gain-of-function variants are associated with pancreatitis, but loss-of-function variants are typically benign." (PMID 39676521, 2024). "Although PVs in CASR and CPA1 have been identified as pancreatitis risk factors in some patients, the majority of described variants in these genes provide a minor contribution to the pathogenesis of CP." (PMID 39172977, 2024). "The best characterized examples of misfolding digestive enzymes are the pancreatitis-associated CPA1 variants." (PMID 35428786, 2022). "The CPA1 N256K mouse model carries the human p.N256K carboxypeptidase A1 (CPA1) mutation, a classic example of a pancreatitis-associated misfolding variant." (PMID 35428786, 2022). "A CPA1 pathogenic pancreatitis allele was identified in 4 patients (0.74%) but is rare in the healthy population (0.044% MAF with no homozygous individuals)." (PMID 33747920, 2021). "The mechanism by which a CPA1 mutation confers an increased risk of pancreatitis involves misfolding-induced endoplasmic reticulum stress, rather than increased trypsin activity." (PMID 33375361, 2020). "A similar mechanism was reported for misfolding PRSS1 and carboxypeptidase A1 (CPA1) mutants, which appear to cause pancreatitis through endoplasmic reticulum stress." (PMID 30408063, 2018). "Next Generation Sequencing was performed to analyze a panel of nine genes associated with pancreatitis (CaSR, CFTR, CPA1, CTRC, CTSB, KRT8, PRSS1, PRSS2, and SPINK1)." (PMID 38927485, 2024). "Individuals who underwent germline multigene testing for pancreatitis susceptibility genes (CASR, CFTR, CPA1, CTRC, PRSS1, SPINK1) through a large commercial laboratory between 2017 and 2022 were included." (PMID 39172977, 2024). "Individuals with hereditary pancreatitis associated with the pancreatitis susceptibility genes (PRSS1, CPA1, CPB2, and CTRC) have also been identified as HRIs, and surveillance for PC is recommended." (PMID 36766654, 2023). "Recently, ethanol feeding was found to accelerate pancreatitis progression in CPA1 Asn256Lys mutant mice." (PMID 33806082, 2021). "Germline testing, currently for recommended etiologic mutations associated with pancreatitis, includes evaluation for pathogenic variants in the CEL, CFTR, CPA1, CTRC, PRSS1, and SPINK1 genes in symptomatic individuals." (PMID 33375361, 2020). "Interestingly, we found no mutations that passed quality control or the expected segregation pattern, in genes known to be associated with pancreatitis such as PRSS1, CFTR, SPINK, CPA1, CTRC, CLDN2, and PLINP." (PMID 36699452, 2022). "The findings raise the possibility that the mild ER stress observed in the pancreas of these mice may not be pathogenic and CPA1 misfolding causes pancreatitis via other mechanisms." (PMID 35428786, 2022). "In cases of CPA1 and CPB2 mutation associated with pancreatic cancer, the individuals do not have to progress through the clinical syndrome of pancreatitis." (PMID 36766654, 2023). "The patient did not have known pancreatitis-associated mutations, such as PRSS1, SPINK1, CTRC, CPA1, or TRPV6." (PMID 36419930, 2022). "There was no appreciable difference between CPA1 N256K and CPA1 N256K × Ddit3-KO mice, indicating similar severity of pancreatitis." (PMID 35428786, 2022).
pancreatic cancer (12 papers, 2017 to 2026). "For example, carboxypeptidase A1 (CPA1) has been found to be overexpressed in pancreatic cancer, while carboxypeptidase E (CPE) has been implicated in the progression of colorectal cancer." (PMID 39170262, 2024). "Although PRSS1 and CPA1 variants have been linked to pancreatic cancer risk, to date variants in other chronic pancreatitis susceptibility genes such as SPINK1 and CFTR have not been consistently found to be risk factors for pancreatic cancer." (PMID 28881607, 2017). "Both CPB1 and CPA1 were reported as susceptible genes of pancreatic cancer." (PMID 33197880, 2020). "Recently, a large scale familial pancreatic cancer sequencing initiative reported the results of whole exome sequencing of 598 kindred and found preliminary evidence that mutations in the pancreatitis susceptibility gene CPA1, contributed to pancreatic cancer risk." (PMID 28881607, 2017). "The CPA1 and CPB1 variants induced by ER stress are associated with pancreatic cancer development." (PMID 35686102, 2022). "Ontological interaction network analysis highlighted the dysregulation of a set of carboxypeptidase family proteins including carboxypeptidase A1 (CPA1) in PDAC and a genome sequencing study identified an association of CPA1 gene with Familial Pancreatic Cancer (FPC)." (PMID 34055623, 2021). "Deleterious mutations in CPA1 were identified in four patients with familial forms of pancreatic cancer but not in controls." (PMID 28881607, 2017). "No CPA1 mutation was found in this region in association with pancreatic cancer." (PMID 36555104, 2022). "The SPINK1 pancreatic cancer pathway was the main pathway expressed following the 24 h triclosan exposure and 120 h 4-nonylphenol exposure, and includes genes such as carboxypeptidase A1 (pancreatic; cpa1), which was dysregulated at 1 nM triclosan, and 10 and 1000 nM 4-nonylphenol." (PMID 35202241, 2022).
chronic pancreatitis (8 papers, 2018 to 2025). A chronic inflammatory process causing damage and fibrosis of the pancreatic parenchyma. "Studies published by Hegyi E. and Sahin-Toth M. clearly demonstrated that mice carrying the CPA1 p.Asn256Lys mutation developed chronic pancreatitis." (PMID 39457082, 2024). "Recurrent variants of the PRSS1, SPINK1, CTRC, CFTR, and CPA1 genes, contributing to the genetic predisposition to chronic pancreatitis development were identified in a cohort of Russian patients." (PMID 37389024, 2023). "In this study, we demonstrate that the transcription factor DDIT3/CHOP plays no significant role in the onset, progression and severity of chronic pancreatitis in CPA1 N256K mice harboring a misfolding CPA1 variant." (PMID 35428786, 2022). "In 2013, sequence analysis of the CPA1 gene in patients with chronic pancreatitis (CP) demonstrated an association between loss-of-function variants and early-onset disease." (PMID 36555104, 2022). "Moreover, as CPA1 is a key enzyme implicated in protein digestion and metabolism, it has been shown to be closely associated with chronic pancreatitis." (PMID 40422699, 2025). "The developed genetic panel (PRSS1, SPINK1, CTRC, CFTR, and CPA1 genes) for identification of genetic risk factors of the chronic pancreatitis development and the usage of the next-generation sequencing technology allowed to specify genetic predictors of the disease development in 61% of patients." (PMID 37389024, 2023). "The aim of the study was to determine the structure of chronic pancreatitis genetic causes in patients living in the European part of Russia by sequencing the entire coding sequence of the PRSS1, SPINK1, CTRC, CFTR, and CPA1 genes." (PMID 37389024, 2023). "In the present study, we generated a CPA1 N256K strain with a global deletion of Ddit3/Chop, and studied the effect of DDIT3/CHOP deficiency in the development and course of chronic pancreatitis." (PMID 35428786, 2022). "We found that CPA1 N256K mice with a global deletion of Ddit3/Chop developed chronic pancreatitis with essentially identical features and timeline as the CPA1 N256K parent strain." (PMID 35428786, 2022). "Taken together, the observations indicate similar severity of chronic pancreatitis in CPA1 N256K and CPA1 N256K × Ddit3-KO mice with respect to macrophage infiltration, acinar-to-ductal metaplasia, and fibrosis." (PMID 35428786, 2022). "Remarkably, CPA1 N256K mice develop spontaneous chronic pancreatitis characterized by acinar atrophy, diffuse fibrosis, regenerative pseudotubular complexes, macrophage infiltration and an increase in plasma amylase activity." (PMID 35428786, 2022). "Surprisingly, CPA1 N256K x Ddit3-KO mice developed chronic pancreatitis with a similar time course and features as the CPA1 N256K parent strain." (PMID 35428786, 2022). "CPA1 N256K mice develop spontaneous, progressive chronic pancreatitis with moderate acinar atrophy, acinar-to-ductal metaplasia, fibrosis, and macrophage infiltration." (PMID 35428786, 2022). "Missense mutations in pancreatic secretory enzymes such as CPA1, PRSS1, CEL and PNLIP may lead to protein misfolding and the development of ER stress, which may predispose to chronic pancreatitis." (PMID 35704637, 2022). "Consequently, heterozygous CPA1 and PRSS1 misfolding mutations are considered as strong risk factors, and are solely capable of inducing chronic pancreatitis." (PMID 35704637, 2022). "Here, we crossed the CPA1 N256K strain with mice containing a global deletion of the Ddit3/Chop gene (Ddit3-KO mice) and evaluated the effect of DDIT3/CHOP deficiency on the course of chronic pancreatitis." (PMID 35428786, 2022). "The findings indicate that genetic deletion of Ddit3/Chop in the CPA1 N256K mice does not protect against onset and progression of chronic pancreatitis, as judged by pancreatic atrophy." (PMID 35428786, 2022).
chronic pancreatitis (continued). "In summary, our study conclusively demonstrates that in the CPA1 N256K mice, onset and progression of chronic pancreatitis is not dependent on the upregulation of Ddit3/Chop." (PMID 35428786, 2022).
breast carcinoma (5 papers, 2018 to 2023). "Hypermethylation of the CPA1 gene in breast cancer cells has been earlier demonstrated, which could lead to its significant downregulation noted here." (PMID 37287543, 2023).
hereditary pancreatitis (5 papers, 2021 to 2024). "Diminished secretion, intracellular retention, and cellular ER stress were subsequently demonstrated for CPA1 variants p.S282P and p.K374E, associated with hereditary pancreatitis." (PMID 36555104, 2022). "Indeed, subsequent studies confirmed that CPA1 variants could cause autosomal dominant hereditary pancreatitis." (PMID 36555104, 2022). "Up to now, the best identified misfolding variants increasing CP risk or causing hereditary pancreatitis have been discovered in PRSS1 and CPA1 genes." (PMID 34065437, 2021).
pancreatic acinar cell carcinoma (3 papers, 2023 to 2025). An adenocarcinoma arising from the pancreas. "The extent of CELA3B immunostaining was significantly linked to the level of CPA1 expression in 16 pancreatic acinar cell cancers (p<0.0001) for which data were available from an earlier study." (PMID 37379306, 2023). "Studies are needed to investigate whether the additional use of CELA3B will increase the diagnostic precision that can be achieved by using CPA1, chymotrypsin, trypsin, or bcl10 for diagnosing acinar cell carcinoma of the pancreas." (PMID 37379306, 2023). "The carboxypeptidase A1 is a highly sensitive marker for pancreatic acinar cell carcinoma." (PMID 37628784, 2023). "Additionally, REG1A and CPA1 show utility in diagnosing mixed pancreatic acinar cell carcinoma/acinar-neuroendocrine carcinoma; notably, we show that CPA1 has the highest reduction in PanNETs, which is consistent with the absence of CPA1 immunohistostaining in PanNETs." (PMID 40217502, 2025).
acute pancreatitis (2 papers, 2024). An acute inflammatory process that leads to necrosis of the pancreatic parenchyma. "In this study, several new mutations of the CPA1 gene were identified, and the relationship between their incidence and the risk of developing acute pancreatitis was determined." (PMID 39457082, 2024). "This evidence supports the high potential of the CPA1 gene mutation as a factor in increasing the risk of developing acute pancreatitis." (PMID 39457082, 2024). "In this work, we highlighted the potential role of CPA1 variants in acute pancreatitis risk." (PMID 39457082, 2024). "There are few reports in the literature on the CPA1 gene and its role in the development of acute pancreatitis and complications following acute pancreatitis." (PMID 39457082, 2024).
cyst (2 papers, 2021 to 2024). A sac-like closed membranous structure that may be empty or contain fluid or amorphous material. "Such comparison resulted in 4 upregulated (CP, CEACAM5, DMBT1, and KRT6A) and 8 downregulated (CEL, CPA1, CPB1, ALB, SERPINA4, CA2, CLU, and AMBP) DEGs secreted in cyst fluid of high-risk IPMNs." (PMID 34790815, 2021).
osteoarthritis (2 papers, 2018 to 2024). A noninflammatory degenerative joint disease occurring chiefly in older persons, characterized by degeneration of the articular cartilage, hypertrophy of bone at the margins and changes in the synovial membrane. "We leveraged the CKP carboxypeptidase A1 inhibitor as a scaffold to construct phage-displayed CKP libraries and subsequently screened these collections against HTRA1, a trimeric serine protease implicated in age-related macular degeneration and osteoarthritis." (PMID 38777835, 2024).
acinar cell carcinoma (1 paper, 2023). "This interaction fits well with the significant association of CELA3B and CPA1 expression in acinar cell carcinomas." (PMID 37379306, 2023). "Reduced CELA3B (and CPA1) expression in acinar cell carcinomas may reflect cellular de-differentiation and could therefore potentially be linked to unfavorable patient prognosis." (PMID 37379306, 2023).
Cognitive impairment (1 paper, 2024). Abnormal cognition is characterized by deficits in thinking, reasoning, or remembering. "Utilizing various algorithms, we identified Cpa1 and Prss1 as potential key genes associated with the cognitive impairment caused by cadmium." (PMID 38287418, 2024).
depression (1 paper, 2025). "The association of trypsin‐2 with depressive symptoms has been reported in a study using proteomic data from the UKB, and adhesion G‐protein‐coupled receptors have been associated with psychiatric disorders in the literature; the role of carboxypeptidase A1 in depression remains unclear." (PMID 40556615, 2025).
fibrosis (1 paper, 2025). the formation of excess fibrous connective tissue in an organ or tissue in a reparative or reactive process. "We assessed pancreatic fibrosis in Cpa1 N256K and Pnlip T221M homozygous mice by Masson’s trichrome staining." (PMID 40992738, 2025).
lung neoplasm (1 paper, 2013). A benign or malignant, primary or metastatic neoplasm involving the lungs. "On the other hand, long arm of chromosome 7 possesses imprinted domain in 7q32-qter which including MEST1, MESTIT1, COPG2IT1loci and a group of four carboxypeptidase A (CPA) genes (CPA1, CPA2, CPA4, CPA5), which are seem to be important (mainly MEST) in the initiation of breast and lung neoplasms." (PMID 23288724, 2013).
pancreatic exocrine insufficiency (1 paper, 2021). "CEL, CPA1, and CPB1 code for carboxyl ester lipase, carboxypeptidase A1, and carboxypeptidase B1, respectively, and their downregulation is again indicative of pancreatic exocrine insufficiency associated with onset of malignancy in benign IPMNs." (PMID 34790815, 2021).
Type 1 diabetes (1 paper, 2025). "We show colocalization of pQTLs for CTRB1, APOBR, IL7R, CPA1, and PNLIPRP1 with Type 1 diabetes GWAS signals, and Mendelian randomization causally implicates each of these five proteins in the aetiology of Type 1 diabetes." (PMID 40263317, 2025).
cancer (16 papers, 2013 to 2025). A tumor composed of atypical neoplastic, often pleomorphic cells that invade other tissues. "More interestingly, most of the signature genes in Cluster 1 were same to those of metastatic cancer cells, including REG1B, MEG3 and CPA1, this was possibly because of the major cell contribution of this cluster from metastatic PDAC." (PMID 34055623, 2021).
tumor (11 papers, 2015 to 2025). "These seem to be specialized responses in which Rgs16 and CPA1 expression is secondary to PDA tumor growth." (PMID 26438693, 2015). "Widespread, high Rgs16::GFP expression in acinar-like cells (co-expressing high CPA1) was sometimes observed in peripheral lobes with edema that sit beyond (proximal to) tumor nodules in KIC pancreata." (PMID 26438693, 2015). "These are specialized responses in which Rgs16 and CPA1 expression is secondary to PDA tumor growth." (PMID 26438693, 2015). "CPA1 and CK19 were used as positive controls for normal and tumor pancreas, respectively." (PMID 40810725, 2025). "Recently, staining for CPA1 (carboxypeptidase A1) and REG1α (lithostathine-1-alpha) were found to have excellent sensitivity and specificity for PACC, essentially excluding the diagnosis if the tumor does not stain positively." (PMID 37538977, 2023).
infection (10 papers, 2010 to 2024). The state of being infected such as from the introduction of a foreign agent such as serum, vaccine, antigenic substance or organism. "TRY, CPA1, CPA2, and CPB1 were considered as hub genes and proven to be repressed throughout the infection process by qRT-PCR." (PMID 31130962, 2019). "For the hub response genes of E. coioides, IL6 and IL1B were induced, while CELA2, TRY, CPA1, CPA2, and CPB1 were repressed throughout the infection process." (PMID 31130962, 2019). "Surprisingly, however, infection with the Cu-resistant triple mutant strain containing the pma1 (L424I), gcs1 (FD481-482del), and cpa1 (A37V) mutations did not reveal any significant difference in virulence or fungal load compared to the control WT strain." (PMID 38814077, 2024).
CPA1 also shares sentences with these, for which no sentence is quoted: colon cancer (4 papers); esophageal adenocarcinoma (3); Barrett esophagus (2); Cirrhosis (2); coccidiosis (2); colorectal cancer (2); embryonal carcinoma (2); age-related macular degeneration (1); arbovirus infection (1); Atrophy (1); bronchiectasis (1); experimental autoimmune encephalomyelitis (1); gallstones (1); gastrointestinal tumors (1); Hepatitis (1); Hyperglycemia (1); Infertility (1); influenza (1); intraductal papillary mucinous neoplasm (1); leishmaniasis (1); liver failure (1); multiple sclerosis (1); Neurodegeneration (1); neuroendocrine carcinoma (1); Obesity (1); orthostatic intolerance (1); parasite infection (1); prostate carcinoma (1); psychiatric disorder (1); Silver-Russell syndrome (1).
A further 4 diseases each share a sentence with CPA1 in 1 paper.